CD2BP2 (CD2 cytoplasmic tail binding protein 2)
Description:
Involved in pre-mRNA splicing as component of the U5 snRNP complex that is involved in spliceosome assembly.
Synonyms: U5-52K; LIN1; Snu40; PPP1R59; FWP010
Tractability: Small molecule: a structure with a bound ligand is known. PROTAC: UniProt records ubiquitination sites on it; ubiquitination databases record sites on it; its protein half-life has been measured.
Gene: Protein-coding gene on chromosome 16 (30,350,767 to 30,355,308, reverse strand). Ensembl gene ENSG00000169217.
Subcellular location: Cytoplasm; Nucleus
Subcellular location (Human Protein Atlas): Nuclear speckles; Cytosol
Pathways (Reactome):
Disease: Dengue Virus-Host Interactions
Gene Ontology:
Molecular function: protein binding; ribonucleoprotein complex binding
Biological process: mRNA splicing, via spliceosome; spliceosomal tri-snRNP complex assembly
Cellular component: cytosol; nuclear speck; nucleoplasm; nucleus; spliceosomal complex; U4/U6 x U5 tri-snRNP complex; U5 snRNP; cytoplasm
Genetic constraint (gnomAD): Loss-of-function variants: 27 observed, 37.51 expected, observed/expected ratio (o/e) 0.72, 90% interval 0.53 to 0.99. The upper end of that interval is the gene's LOEUF score, 0.99, which puts it in group 4 of 6, group 1 being the genes least tolerant of losing a copy. Missense variants: 497 observed, 463.82 expected, observed/expected ratio (o/e) 1.07, 90% interval 1 to 1.15. Synonymous variants: 212 observed, 180.16 expected, observed/expected ratio (o/e) 1.18, 90% interval 1.05 to 1.32.
Homologues: Orthologues: chimpanzee CD2BP2 (98% identical), macaque CD2BP2 (97% identical), dog CD2BP2 (93% identical), rabbit CD2BP2 (92% identical), mouse Cd2bp2 (91% identical), pig CD2BP2 (91% identical), guinea pig CD2BP2 (90% identical), rat Cd2bp2 (90% identical), tropical clawed frog cd2bp2 (52% identical), zebrafish cd2bp2 (52% identical), Drosophila melanogaster holn1 (33% identical), Caenorhabditis elegans teg-1 (29% identical).
Diseases named in the same sentence as CD2BP2 in open-access papers:
CD2BP2 is named in the same sentence as 9 diseases in open-access papers, as found by Europe PMC text mining. Sharing a sentence is not in itself a finding about the gene and the disease. The quoted sentences say what the papers report.
Autoimmunity (1 paper, 2024). The occurrence of an immune reaction against the organism's own cells or tissues. "Potentially, splicing inhibition targeting U5 snRNP components such as CD2BP2/U5–52K, could be exploited in similar ways to restrict T cell growth in leukemia or autoimmunity." (PMID 39308865, 2024).
lymphopenia (1 paper, 2024). Reduction in the number of lymphocytes. "CD2BP2/U5–52K deletion in T cells results in a strong lymphopenia that is caused by reduced proliferation and enhanced apoptosis of T cells." (PMID 39308865, 2024). "Increased T cell lymphopenia and T cell death are observed upon depletion of CD2BP2/U5–52K." (PMID 39308865, 2024). "Considering that the lack of CD2BP2/U5–52K induces T cell lymphopenia in both spleen and lymph nodes, we wondered whether the ratio between naïve and memory T cells in both CD4+ and CD8+ populations is affected in the absence of CD2BP2/U5–52K." (PMID 39308865, 2024).
T-cell ALL (1 paper, 2024). "We speculate that the association of USP44 with CD2BP2 may play a role in T-cell ALL." (PMID 39767807, 2024).
viral infection (1 paper, 2016). "NS5 alone or in the context of viral infection binds to CD2BP2 and DDX23, core components of U5 snRNP, and incorporates in active spliceosomes." (PMID 27575636, 2016). "In particular, we show that NS5 alone, or in the context of viral infection, interacts with core components of the U5 snRNP particle, CD2BP2 and DDX23, alters the inclusion/exclusion ratio of alternative splicing events, and changes mRNA isoform abundance of known antiviral factors." (PMID 27575636, 2016).
infection (4 papers, 2015 to 2022). The state of being infected such as from the introduction of a foreign agent such as serum, vaccine, antigenic substance or organism. "This RNA-dependent RNA polymerase (RdRp) interacts with CD2BP2 and DDX23 from the U5 snRNP, allowing modulation of cellular AS during infection benefiting the replication of Dengue virus." (PMID 35489070, 2022). "In contrast, no significant changes were observed for CD2BP2, DDX23, EFTUD2, SNRNP40 (U5 snRNP components) or SF3A2 (U2 snRNP component) levels up to 48 hours of infection as compared with those in uninfected cells." (PMID 27575636, 2016).
tumor (3 papers, 2017 to 2024).
CD2BP2 also shares sentences with these, for which no sentence is quoted: chronic kidney disease (1 paper); leukemia (1); malaria (1).